CDH1 (cadherin 1)
Diseases named in the same sentence as CDH1 in open-access papers (continued):
Sharing a sentence is not in itself a finding about the gene and the disease.
Nephropathy (3 papers, 2020 to 2023). A nonspecific term referring to disease or damage of the kidneys. "Our data suggest the following urinary excretion thresholds for CDH1: in healthy volunteers, the range of CDH1 excretion level is about 18.6 ± 8.7 ng/mL, whereas in diabetic patients at risk of developing nephropathy, the excretion level increases in early stage to >40 ng/mL." (PMID 32121033, 2020). "The excretion level of CDH1 increased towards nephropathy, it ranges from 18.6 ± 8.7 ng/mL by healthy controls and increased significantly (>45 ng/mL) for DM patients at risk to develop nephropathy and to 77.8 ± 55.2 ng/mL for DN Macro." (PMID 32121033, 2020). "The label-free quantification and immunological data form the longitudinal follow-up study demonstrated a strong correlation between the urinary CDH1 levels and the progression toward nephropathy in diabetic patients." (PMID 32121033, 2020). "ELISA data confirmed the potential of CDH1 as discriminating parameter between different stages of nephropathy in diabetic patients." (PMID 32121033, 2020).
orofacial cleft (3 papers, 2014 to 2024). A disorder of facial skeleton that is characterized by cleft lip and/or cleft palate that result in feeding, speech and hearing problems caused by failures during development. "The recurrent CDH1 variant c.760G>A was previously reported in 21 individuals from six families, of whom 15 individuals showed orofacial clefts." (PMID 39596675, 2024). "Currently, more than 112 disease-causing mutations germline mutations (with a “DM” flag) associated with cancer or orofacial clefting phenotypes in the CDH1 gene are listed in Human Gene Mutation Database(HGMD) professional (2021.04)." (PMID 37393258, 2023). "In France, approximately 6 % of registered CDH1 germline mutation carriers have an orofacial cleft." (PMID 24838934, 2014).
schizophrenia (3 papers, 2014 to 2023). A major psychotic disorder characterized by abnormalities in the perception or expression of reality. "In addition, previous studies have shown that changes in the levels of CNTN1, CDH1, and other cell adhesion proteins in peripheral blood are associated with deficit schizophrenia, which may also be related to hypoxia." (PMID 37576864, 2023).
scleroderma (3 papers, 2015 to 2022). Scleroderma is a rare autoimmune connective tissue disorder characterized by abnormal hardening of the skin and, sometimes, other organs. "However, mesenchymal–epithelial transition (MET) associated proteins such as SCRIB, DSP, TJP1, CDH1, DLG1, and TJP2 were downregulated in scleroderma skin, indicating the high severity of skin fibrosis in mice with scleroderma." (PMID 35315234, 2022).
Stroke (3 papers, 2020 to 2022). Sudden impairment of blood flow to a part of the brain due to occlusion or rupture of an artery to the brain. "Cdh1 is the activator of APC/C and cyclin B1 is one substrate of APC/C–Cdh1, whose nuclear level is increased in affected neurons of stroke patients." (PMID 36438186, 2022).
acute leukemia (2 papers, 2023 to 2024). A clonal (malignant) hematopoietic disorder with an acute onset, affecting the bone marrow and the peripheral blood. "Consistently, E-cadherin expression was found to be suppressed by methylation of the 5′ CpG island of the cdh1 promoter in acute leukemia." (PMID 38396852, 2024).
acute promyelocytic leukemia (2 papers, 2016 to 2022). An aggressive form of acute myeloid leukemia (AML), characterized by arrest of leukocyte differentiation at the promyelocyte stage, due to a specific chromosomal translocation t(15;17) in myeloid cells. "In contrast, acute promyelocytic leukemia (APL) blasts are resistant to differentiation block mediated by low Cdh1-expression." (PMID 35832196, 2022).
ampullary cancer (2 papers, 2014 to 2020). "The most frequent gene alteration in ampullary cancer was found in APC (23%), followed by CTNNB1 (9%), RNF43 (8%), CDH1 (1.9%), and WNT1 (1.3%)." (PMID 32764696, 2020).
anemia (2 papers, 2021 to 2022). A reduction in the number of red blood cells, the amount of hemoglobin, and/or the volume of packed red blood cells. "Consistently, Cdh1 ablation leads to mild but persistent anemia from birth to adulthood." (PMID 35729193, 2022). "We first tested whether or not newborn mice lacking Cdh1 expression only in hematopoietic cells could recapitulate the mild anemia phenotype observed in Cdh1-null pups." (PMID 35729193, 2022). "Recently, it was shown that severe anemia resulted in a disproportionate and persistent increase in intestinal permeability due to the disruption of epithelial adherens junctions, mediated via depletion of E-cadherin (Cdh1) mRNA." (PMID 33802302, 2021). "As deletion of either Cdh1 or Rb on their own leads to moderate anemia compatible with life, it is tempting to speculate that both tumor suppressors work redundantly to sustain red blood cell homeostasis, and that a combined inactivation of Rb and Cdh1 would dramatically blunt erythropoiesis." (PMID 35729193, 2022). "Using Cdh1-deficient mouse embryos and adult mice specifically depleted of Cdh1 in the hematopoietic lineage, we uncovered inefficient terminal erythroid differentiation during fetal and adult erythropoiesis in the absence of Cdh1 resulting in persistent mild anemia from birth to adulthood." (PMID 35729193, 2022). "It is possible that the timing of Cdh1 deletion in HSCs might determine whether or not the anemia phenotype is manifested." (PMID 35729193, 2022). "Reduced hematocrit values, red blood cell counts, and hemoglobin concentration were found in Cdh1 KO pups, indicating mild anemia in the absence of Cdh1 and suggesting a role for APC/C-Cdh1 in erythropoiesis." (PMID 35729193, 2022).
apocrine carcinoma (2 papers, 2006 to 2022). "Based on a nested PCR approach, we detected CDH1 hypermethylation in 52/71 IDCs, 4/5 ILCs and in the apocrine carcinoma." (PMID 16512896, 2006).
choanal atresia (2 papers, 2020 to 2022). Choanal atresia (CA) is a congenital anomaly of the posterior nasal airway characterized by the obstruction of one (unilateral) or both (bilateral) choanal aperture(s), with clinical manifestations ranging from acute respiratory distress to chronic nasal obstruction. "Few BCD cases have been reported in the Asian population; there was only one literature report on a Japanese girl who had a cleft lip and palate, choanal atresia, tetralogy of Fallot, and a neural tube defect, which was caused by a missense variant in the CDH1 gene." (PMID 36552944, 2022).
chromophobe renal cell carcinoma (2 papers, 2023). Chromophobe renal cell carcinoma is a rare subtype of renal cell carcinoma, originating from the intercalating cells of the collecting ducts and macroscopically manifesting as a well-circumscribed, highly lobulated, solid tumor that is usually diagnosed at an early stage. "In the TCGA chromophobe renal cell carcinoma dataset, originating also from distal tubules, TFCP2L1 and MITF expression correlated with that of CDH1." (PMID 37236926, 2023).
Cognitive Deficits (2 papers, 2017 to 2022). "Moreover, bilateral intra-hippocampal injection with Cdh1-encoding lentivirus attenuated long-term cognitive deficits after exposure to isoflurane in developing rats." (PMID 29218001, 2017). "Recently, we found that APC/C-Cdh1 targets Rock2 for proteasomal degradation in neurons, and that the loss of Cdh1 causes Rock2 stabilization and activation, triggering dendrite disruption, and dendritic spine and synapse loss in the adult brain following neurodegeneration and cognitive impairment." (PMID 35496276, 2022). "Thus, here we identify a novel Cdh1-Rock2 pathway that is involved in Aβ neurotoxicity, which may open a new avenue for the development of therapeutic strategies to combat cognitive impairment in AD." (PMID 35496276, 2022).
colorectal signet ring cell carcinoma (2 papers, 2016 to 2023). An invasive colorectal adenocarcinoma characterized by the presence of malignant glandular epithelial cells with prominent intracytoplasmic mucin resulting in the displacement of the nuclei. "We also observed a colorectal signet ring cell carcinoma in a CDH1 carrier at 30 years old." (PMID 37761816, 2023).
craniopharyngioma (2 papers, 2022 to 2025). A benign, partly cystic, epithelial tumor of the sellar region, presumably derived from Rathke pouch epithelium. "Similarly, the association between pathways in cancer and ACPs has not been reported, but the three most significant key genes (CDH1, WNT5A, and SHH) have been closely/positively associated with craniopharyngioma." (PMID 36387067, 2022).
endometrioid ovarian cancers (2 papers, 2015 to 2021). "From a histological perspective, high-grade serous and endometrioid ovarian cancers have the lowest CDH1 expression." (PMID 26549805, 2015).
esophageal tumor (2 papers, 2011 to 2016). "Further studies are required to determine whether chromosomal losses occurred in the CDH1 and CTNNB1 loci in the esophageal tumor tissues that were examined in this study." (PMID 27600761, 2016).
Fanconi anemia (2 papers, 2015 to 2018). Fanconi anemia (FA) is a hereditary DNA repair disorder characterized by progressive pancytopenia with bone marrow failure, variable congenital malformations and predisposition to develop hematological or solid tumors.
gastrointestinal carcinoma (2 papers, 2010 to 2020). "Consistent with METHY analysis, a pan-gastrointestinal carcinoma cluster with COAD/READ-STAD was gathered in C2, which had high level of CDH1, CLDN7 and TYRO3, and a low level of CAV1." (PMID 32874774, 2020).
Hyperinsulinemia (2 papers, 2023 to 2025). An increased concentration of insulin in the blood. "Under hyperglycemic conditions, hyperinsulinemia slightly upregulated CDH1 (FCHG, ins = 1.23) and COL1A1 expression (FCHG, ins = 0.75) compared to the respective untreated hyperglycemic controls, whereas MMP9 levels (FCHG, ins = 0.56) were downregulated." (PMID 37313172, 2023). "In contrast, CDH1 (FCHG, ins = 1.52), CDKN1A (FCHG, ins = 2.87), PTEN (FCHG, ins = 1.61) and MMP9 (FCHG, ins = 0.71) were slightly downregulated during hyperinsulinemia under the influence of a hyperglycemic environment, when compared to the respective untreated hyperglycemic control samples." (PMID 37313172, 2023).
Hypodontia (2 papers, 2022 to 2023). The absence of five or less teeth from the normal series by a failure to develop. "As a newly identified syndromic tooth agenesis causative gene, CDH1 can serve as a potential causative gene for non-syndromic tooth agenesis." (PMID 36552944, 2022). "In addition, we also suggested that CDH1 can be used as a potential non-syndromic tooth agenesis pathogenic gene for screening." (PMID 36552944, 2022).
male infertility (2 papers, 2016 to 2018). The inability of the male to effect fertilization of an ovum after a specified period of unprotected intercourse. "Most SNP-populated genes related to male infertility include HLA-DQB1 (20 SNPs), HLA-DRB1 (15 SNPs), MTHFR (10 SNPs), BRCA2 (9 SNPs), ACE (8 SNPs), CFTR (6 SNPs), CDH1 (6 SNPs), SRD5A2 (6 SNPs), HLA-DQA1 (5 SNPs) and MMP9 (5 SNPs)." (PMID 29263816, 2016).
myeloid leukemia (2 papers, 2016). A clonal proliferation of myeloid cells and their precursors in the bone marrow, peripheral blood, and spleen. "Accordingly, we found increased Cdh1 expression upon Skp2-kd in HL-60 and NB4 myeloid leukemia cells." (PMID 27374082, 2016).
oligodendroglioma (2 papers, 2021 to 2025). A well-differentiated (WHO grade II), diffusely infiltrating neuroglial tumor, typically located in the cerebral hemispheres. "CDH1 was most often mutated in oligodendrogliomas, 2.19% (3/137 cases), and GBMs followed with 1.69% (28 cases)." (PMID 40679044, 2025). "For instance, CDH1 mutations predominated in oligodendroglioma and GBM, while CDH2 mutations were not reported for oligodendroglioma." (PMID 40679044, 2025). "As a result, we identified two families with rare germline variants, p.(A592T) or p.(A817V), in the E-cadherin gene CDH1 that co-segregate with the tumor phenotype, consisting primarily of oligodendrogliomas, WHO grade II/III, IDH-mutant, 1p/19q-codeleted (ODs)." (PMID 33929593, 2021).
osteoporosis (2 papers, 2023 to 2025). A condition of reduced bone mass, with decreased cortical thickness and a decrease in the number and size of the trabeculae of cancellous bone (but normal chemical composition), resulting in increased fracture incidence. "In fact, in the bone marrow samples of patients with osteoporosis, Cdh1 and Fosl1 were significantly upregulated while Ubap2 was significantly downregulated." (PMID 37339951, 2023). "This suggests that modulation of Cdh1 could be a potential therapeutic option for treating osteoporosis." (PMID 40919176, 2025). "mRNA levels of both CDH1 and FOSL1 were significantly higher in bone marrow-derived buffy coat from patients with osteoporosis than that in normal controls." (PMID 37339951, 2023).
ovarian clear cell cancer (2 papers, 2021 to 2025). An invasive malignant neoplasm that arises from the ovary and is characterized by a predominance of clear and hobnail malignant epithelial cells. "In another study, overexpression of RALYL suppresses the progression of ovarian clear cell carcinoma by inhibiting MAPK and CDH1 signaling pathways." (PMID 40052233, 2025).
plasmacytoma (2 papers, 2015 to 2018). Plasmacytoma is a localized mass of neoplastic monoclonal plasma cells that represents approximately 5% of all plasma cell neoplasms. "While SHP1 and CDKN2A were hypermethylated in both plasmacytomas, CDH1 hypermethylation was detected only in the chest wall." (PMID 30572945, 2018).
type 1 diabetes (2 papers, 2013 to 2021). "Intriguingly, the CDH1 gene, which encodes human E-cadherin, is located on chromosome 16q22.1, a locus that has been implicated in susceptibility to type 1 diabetes, and various CAMs have been implicated in the autoimmune pathogenesis of type 1 diabtes." (PMID 24278783, 2013).
uterine carcinosarcoma (2 papers, 2013 to 2024). A usually aggressive malignant neoplasm arising from the uterine corpus and less often the cervix. "Molecular evaluation revealed a characteristic CDH1 mutation within the ILC and a PI3KCA mutation within the uterine carcinosarcoma, both of which have been linked to epithelial-to-mesenchymal transitions." (PMID 39076998, 2024).
Zinc deficiency (2 papers, 2022 to 2025). A deficiency of the essential metal Zinc; an essential cofactor for many enzymes. "The levels of CDH2, Vimentin, and SNAIL were significantly downregulated compared with the zinc deficiency group, while CDH1 expression was restored." (PMID 39028478, 2025). "Specifically, our findings demonstrate that zinc deficiency significantly upregulates the expression of CDH2, Vimentin, and Snail in renal tissues while downregulating CDH1." (PMID 39028478, 2025).
adenosarcoma (1 paper, 2017). A low grade malignant neoplasm characterized by the presence of a benign epithelial component (tubular and cleft-like glands) and a low grade sarcomatous component that contains varying amounts of fibrous and smooth muscle tissues. "TGFβ induces EMT in many types of cells in vitro, including human ovarian epithelial and adenosarcoma cells, by enhancing Snai1 (Snail) expression leading to inhibition of Cdh1 (E-cadherin)." (PMID 29100356, 2017).
alcohol abuse (1 paper, 2020). The use of alcoholic beverages to excess, either on individual occasions ("binge drinking") or as a regular practice. "Thus, the heterogeneity of the manifestation for the same PV of the CDH1 gene suggests that exogenous factors (smoking, alcohol abuse), endogenous factors (microbiom, hormones), or polygenic causes could be involved in the etiology of the different clinical presentations." (PMID 33322525, 2020).
behavioral disorders (1 paper, 2020). "Beyond the known phenotypes associated with CTNND1 and CDH1, we note the novel phenotypes seen in our patients, which include the heart anomalies and behavioral disorders." (PMID 32196547, 2020).
chronic myeloid leukemia (1 paper, 2022). "Tyrosine kinase inhibitors, which have changed the management of chronic myeloid leukemia (CML) patients during the last 10 years, control cell cycle and apoptosis through several mechanisms, including the regulation of CDH1 levels." (PMID 35490245, 2022).
colorectal polyps (1 paper, 2025). "However, consistent with our findings, recent studies have established that carrying a variant in this gene generates a higher predisposition to colorectal polyps, suggesting a potential association between CDH1 variants and CRC risk." (PMID 40458721, 2025).
congenital malformations (1 paper, 2020). "Moreover, given the pleiotropic nature of CDH1 variants, a careful interpretation of data should take into account the disease context, including diffuse GC, LBC, or congenital malformations, so a proper management can be offered to CDH1 variant carriers." (PMID 32560361, 2020).
cryptococcosis (1 paper, 2024). An acute or chronic, localized or disseminated infection by Cryptococcus neoformans. "Furthermore, our results from the murine inhalation model of the systemic infection of cryptococcosis also indicate that Cdh1 plays a significant role in the pathogenicity of C. neoformans." (PMID 39728387, 2024).
degenerative myopia (1 paper, 2025). "CDH1 (ENSP00000261769) is also one of the most important gene associated with degenerative myopia and has been selected by both methods." (PMID 40110040, 2025).
diabetic retinopathy (1 paper, 2022). "In this case, CDH1 and CDH2 mRNAs produce calcium-dependent adhesion proteins (E-cadherin and N-cadherin), which play a fundamental role in intercellular adhesion, and abnormal expression of these genes causes various diseases such as DN, diabetic retinopathy, and epithelial-derived solid tumors." (PMID 35363774, 2022).
diffuse type adenocarcinoma (1 paper, 2018). An adenocarcinoma characterized by the presence of a diffuse cellular infiltrate which is composed of poorly cohesive cells with minimal or no glandular formations. "Since the reduction of E-cadherin expression in tumor tissue and mutations in the CDH1 gene (codifying for E-cadherin) are strongly associated with diffuse-type adenocarcinoma, we also performed the sequence analysis of germline CDH1 gene." (PMID 29882764, 2018).
dysembryoplastic neuroepithelial tumor (1 paper, 2020). A benign glial-neuronal neoplasm. "Mutations in CDH1 (A298T) and FGFR1 (K656_T658 > MTP) were identified by targeted sequencing in one patient with a low-grade glioneuronal neoplasm (dysembryoplastic neuroepithelial tumor [DNET]-like) and were conserved at recurrence (Patient #45)." (PMID 33153497, 2020).
endometrial stromal sarcoma (1 paper, 2024). "Few studies have investigated ATM, BLM, and CDH1 gene mutations in high-grade endometrial stromal sarcoma." (PMID 39009979, 2024).
epithelial colon tumors (1 paper, 2017). "As a result, we examined in detail the impact of FOXA factors on enhancer regions at the CDH1, CDX2 and EPHB3 genes which are among the signature genes of epithelial colon tumors and which are downregulated in Snail1-expressing LS174T cells." (PMID 29155818, 2017).
eye cancers (1 paper, 2022). "Although it is not clear how CDH1 expression results in a decrease in NANOS1 level, this negative correlation between NANOS1 and CDH1 expression on RNA level is observed also in multiple cancer cell lines, representing breast, colon, brain, skin, and eye cancers." (PMID 36012673, 2022).
familial disease (1 paper, 2024). "Somatic alterations in RHOA and CDH1 have been reported in aggressive diffuse GC and are generally associated with familial disease." (PMID 39200369, 2024).